XIST (X inactive specific transcript)
Diseases named in the same sentence as XIST in open-access papers (continued):
Sharing a sentence is not in itself a finding about the gene and the disease.
osteosarcoma (continued). "BMSCs derived exosomal XIST binds miR-655 to promote ACLY expression, and then enhances β-catenin signal activity, which is another mechanism of XIST to accelerate the growth and metastasis of osteosarcoma." (PMID 36309693, 2022). "Interestingly, XIST acted as a decoy for miR‐195‐5p and thereby to alter YAP expression, implicating a regulatory role of XIST/miR‐195‐5p/YAP network in osteosarcoma progression." (PMID 32779318, 2020). "However, the effect aberrant XIST expression on the prognosis of patients was still controversial in HCC and osteosarcoma." (PMID 29556138, 2018). "In-depth mechanism study showed that BMSCs derived exosomal XIST combined with miR-655 to increase the protein level of ACLY, which led to lipid deposition and activate β-catenin signal to promote the proliferation, migration and invasion of osteosarcoma cells." (PMID 36309693, 2022). "However, patients with elder age, larger tumor size and distant metastasis were accompanied by overexpression of TUG1 and XIST, which further demonstrated the negative role of lncRNA TUG1 and XIST in osteosarcoma progression." (PMID 33639865, 2021).
autoimmune disease (16 papers, 2019 to 2026). A disorder resulting from loss of function or tissue destruction of an organ or multiple organs, arising from humoral or cellular immune responses of the individual to their own tissue constituents. "Studies have indicated the potential involvement of XIST in the predisposition of females to many neurodegenerative and autoimmune disorders, as well as cancer and cardiovascular diseases, in addition to its essential function in dose compensation in females." (PMID 40407589, 2025). "The notion that XIST RNP acts as an autoantigen to induce autoimmunity implies that all female-associated autoimmune diseases are caused by the production of autoantibodies to XIST RNP, regardless of the disease phenotype." (PMID 38665922, 2024). "These escaping genes (including XIST) underlie sex-biassed susceptibility to certain diseases, such as autoimmune diseases." (PMID 39140247, 2024). "Recent advances in our comprehension of lncRNA function have revealed that dysfunction of XIST may be closely linked to the pathogenesis of several neurodegenerative and autoimmune diseases." (PMID 40407589, 2025). "Because the function of XIST is to inactivate one of the two X chromosomes in females, it is not expressed in males, explaining why XIST is a strong candidate for underlying female predominance in autoimmune diseases." (PMID 38665922, 2024). "Finally, the most upregulated gene in our data, XIST, is involved in X-linked silencing in cells by regulating epigenetic processes and has been associated with several autoimmune diseases that are female predominant, such as multiple sclerosis and systemic sclerosis." (PMID 39408800, 2024). "Moreover, this provides a potential argument that XIST may be a contributing factor in mammalian females’ ability to better combat pathogens comparative to males and their increased predisposition to autoimmune disorders." (PMID 31336952, 2019). "Aberrant overexpression and/or cytoplasmic translocation of XIST allow it to engage miRNAs and disrupt cellular homeostasis and contribute to pathogenesis of cancer, autoimmune diseases, and cardiovascular diseases." (PMID 41601966, 2026). "In the context of another autoimmune disease, systemic lupus erythematosus (SLE), the abnormal localization of XIST has been associated with changes in T cells among SLE patients, as well as alterations in XIST levels in SLE patients." (PMID 40407589, 2025). "This evidence indicates the critical role of m6A and XIST-related mechanisms in autoimmune diseases." (PMID 39497033, 2024). "Since XIST is a ribonucleoprotein (RNP) enriched with protein antigens targeted in autoimmune diseases, Dou et." (PMID 38665922, 2024). "First, the limited immunogenicity of Barr bodies in autoimmune diseases challenges the notion that XIST RNP drives autoimmunity in humans by acting as an autoantigen." (PMID 38665922, 2024). "Dysregulated m6A modifications on XIST correlate with autoimmune disease progression, such as systemic lupus erythematosus (SLE) and rheumatoid arthritis (RA)." (PMID 39497033, 2024). "Its expression in XIST-depleted B cells leads to the generation of a female-specific B cell population that accumulates with age and can also be observed in autoimmune disorders." (PMID 39471841, 2024). "The upregulation of XIST, seen in other female-predominant autoimmune diseases, likely plays a crucial role in vascular dysregulation and LS progression." (PMID 39408800, 2024). "Given that XIST was the most upregulated gene in our LS dataset and that LS is primarily a female autoimmune disorder, we considered it of particular interest in our study." (PMID 39408800, 2024). "The upregulation of XIST, which is also seen in other female-predominant autoimmune diseases, likely plays a central role in vascular dysregulation and LS progression." (PMID 39408800, 2024).
autoimmune disease (continued). "As CD40L and CXCR3 are strongly associated with the autoimmune disorder systemic lupus erythematosus (SLE), this inspired further work to characterise potential links between XIST localisation and the autoimmune disease." (PMID 31336952, 2019). "Understanding the role of XIST in endothelial cells of LS patients could provide insights into the immune response, especially given its significance in SSc and other autoimmune disease that predominately affect females." (PMID 39408800, 2024). "Therefore, XIST deregulation leads to autoimmune diseases in females, representing 80% of the people affected by these diseases." (PMID 35860270, 2022). "Interestingly, unlike wild-type male mice, two-thirds of males expressing XIST developed severe multi-organ disease after pristane injection, which was comparable to pristane-induced lupus in females, demonstrating that XIST overexpression predisposes to autoimmune disease development." (PMID 38665922, 2024). "Collectively, all of this evidence suggests that XIST and miRNA155 may be the upstream regulators of TAK1, which in turn triggers inflammatory and immunological cascades in autoimmune diseases such as APS." (PMID 37914735, 2023). "Additionally, although lncRNA XIST has not been reported in RA, it has been reported to be upregulated in another autoimmune disease, Sjogren's syndrome." (PMID 33407587, 2021). "However, while the protein targets of these antibodies, as well as autoantibodies found in autoimmune diseases in humans, are components of the XIST RNP, they are not XIST-specific." (PMID 38665922, 2024).
systemic lupus erythematosus (15 papers, 2019 to 2026). An autoimmune multi-organ disease typically associated with vasculopathy and autoantibody production. "In another study, high XIST expression has been found to be associated with the CD4-positive T cell level in systemic lupus erythematosus patients." (PMID 38265097, 2024). "Dysregulation of XIST in both naive B and T cells promoted autoimmunity due to loss of proper maintenance in systemic lupus erythematosus (SLE) and primary biliary cholangitis (PBC), respectively." (PMID 38949020, 2024). "XIST RNA levels were high in the blood leukocytes of females with systemic lupus erythematosus versus controls and correlated positively with increased production of interferon-α and disease activity." (PMID 39639337, 2024). "Further studies show that reduced XIST expression leads to female-specific lupus-like autoimmunity, while extracellular xist RNA itself may stimulate TLR-7 as an endogenous ligand." (PMID 41283475, 2025). "Previous work proposed that XIST may be responsible for sex bias in systemic lupus erythematosus and rheumatoid arthritis, mainly because of the dynamic regulation of XIST/Xist in lymphoid cells from humans and mice." (PMID 39639337, 2024). "We therefore examined the relationship between XIST expression and disease activity, as measured by the physician’s global assessment (PGA) and the systemic lupus erythematosus disease activity index (SLEDAI)." (PMID 37733447, 2023). "Indeed, nonrandom XCI, elevated gene escape from XCI, and the autoimmune potential of the XIST RNP complex have been suggested to contribute to auto-immune diseases, such as lupus." (PMID 39375734, 2024). "Moreover, the studies demonstrated that XIST acts as an inducer of interferon-α, rather than as an interferon stimulated gene, a finding consistent with a pro-inflammatory role of XIST in systemic lupus erythematosus." (PMID 39639337, 2024). "The hypothesis that an increased immunogenicity of XIST RNP complexes that is present only in females underlies female-biased autoimmunity has recently been evaluated in a pristane-inducible mouse model for systemic lupus erythematosus (SLE), in which XIST was overexpressed in male animals." (PMID 38791207, 2024).
myocardial infarction (14 papers, 2020 to 2026). Gross necrosis of the myocardium, as a result of interruption of the blood supply to the area, as in coronary thrombosis. "Many reports have indicated that lncRNA XIST plays critical role in cell proliferation, differentiation, and genome maintenance, and we noticed that LncRNA XIST has been reported to be associated with myocardial infarction and cardiac hypertrophy." (PMID 32315985, 2020). "Increased levels of XIST RNA were reported in a model of myocardial infarction, where sequestration of miR-101a-3p by XIST de-repressed transcription factor FOS and increased cardiomyocyte apoptosis." (PMID 41601966, 2026). "Unbiased analyses of the lncRNA-miRNA-mRNA regulatory networks identified blood XIST RNA levels as a biomarker for acute myocardial infarction." (PMID 41601966, 2026). "Our recent findings revealed increased expression levels of the lncRNAs XIST (X-inactive specific transcript) and MIAT (myocardial infarction-associated transcript) in leiomyomas." (PMID 38279317, 2024). "The XIST expression was markedly raised in the I/R model group while decreased in the emodin group, and the overexpression of XIST reversed the protective effect of emodin on myocardial infarction, oxidative stress, and cardiomyocyte apoptosis." (PMID 36760350, 2023). "Similar effects were observed in myocardial cell apoptosis in acute myocardial infarction model rats through XIST/miR-449/Notch1." (PMID 35054794, 2022). "In the context of cardiovascular diseases, XIST was found upregulated in coronary heart disease tissues and post-myocardial infarction cells, where it suppressed cell proliferation and promoted apoptosis, at least partly by XIST/miR-130-3p/PDE4D." (PMID 35054794, 2022). "In vivo experiments unveiled that knockdown of XIST can inhibit myocardial cell apoptosis in acute myocardial infarction rat model by adjusting miR-449." (PMID 34362365, 2021). "To understand the role of XIST in the mice model of myocardial infarction, we performed MI in the mice model and evaluated the effects of inhibiting XIST on cardiac damage by TTC staining." (PMID 32315985, 2020). "In the present study, we revealed the lncRNA-miRNA-mRNA axis that participate in myocardial infarction, which was the XIST-miR-101a-3p-FOS axis." (PMID 32315985, 2020). "Silencing XIST expression improved cell viability and suppressed apoptosis in vitro and inhibited myocardial infarction by reducing the level of c-FOS and apoptosis-related proteins in vivo." (PMID 32315985, 2020). "In conclusion, our present study reveals that lncRNA XIST is integrated into the machinery of myocardial infarction, and that XIST can affect myocardial infarction and cardiomyocyte apoptosis by regulating the expression of FOS." (PMID 32315985, 2020). "Our findings suggest that XIST is involved in MI, modulation of its level can be used as a new strategy or potential target in the treatment of myocardial infarction." (PMID 32315985, 2020). "After 24 h of myocardial infarction, the level of XIST was significantly increased in the infarct area (P<0.05)." (PMID 32315985, 2020). "Using a murine model of myocardial infarction, we first evaluated the level of the XIST by qRT-PCR in mice heart samples." (PMID 32315985, 2020). "The pathological contexts when XIST is mis-localized to the cytoplasm (e.g., certain cancers or myocardial infarction) prompt consideration of targeting XIST with gapmer ASOs that are particularly effective due to their compatibility with RNase H1 activity in the nucleus and cytoplasm." (PMID 41601966, 2026). "Based on this part of the experimental results, we concluded that decreasing XIST expression could protect mice from myocardial infarction and cardiomyocyte apoptosis in some degree by down-regulating the expression of c-FOS and apoptosis-related proteins." (PMID 32315985, 2020).
myocardial infarction (continued). "Accordingly, XIST may suppress the proliferation of post-myocardial infarction cells and promote apoptosis by targeting miR-130a-3p and PDE4D in a straight line." (PMID 31942979, 2020). "In addition, XIST promotes the development of myocardial infarction through a similar approach." (PMID 38699233, 2024). "However, in post-XCI somatic tissues, dysregulation of XIST has recently been documented to play a role in chronic inflammatory diseases such as atherosclerosis, coronary artery disease, myocardial infarction, Alzheimer’s disease, Parkinson disease, among others." (PMID 36922677, 2023). "Despite its original role in XCI, XIST also participates in the regulation of cell growth and development as well as the progression of tumors and other human diseases, such as Alzheimer’s, acute myocardial infarction, cardiac morbidities, myocardial infarction, and acute kidney injury." (PMID 34771549, 2021). "In consistent with these findings, here we reported that suppression of XIST improved the viability of NMCMs that deprived of oxygen and reduced myocardial infarction area due to MI in the hearts of mice." (PMID 32315985, 2020). "However, it remains unclear whether lncRNAs especially XIST participate in the regulation of myocardial infarction, the molecular mechanism and pathway of myocardial infarction need further study, which may have clinical significance." (PMID 32315985, 2020). "Our results showed that the mice treated with XIST-siRNA adenoviruses exhibited a significant reduction in myocardial infarction sizes (INF/AAR) in response to MI as determined by TTC staining (P<0.05)." (PMID 32315985, 2020). "For example, a PMO-TSB targeting the miR-101a-3p binding site on XIST could restore miR-101a-3p availability to suppress FOS, thereby reducing cardiomyocyte apoptosis following myocardial infarction." (PMID 41601966, 2026). "XIST regulates FOS expression and the consequent myocardial infarction through miR-101a-3p." (PMID 32315985, 2020). "However, the questions about specificity of this biomarker and the origin of XIST in blood after myocardial infarction have not been addressed." (PMID 41601966, 2026). "In addition, X-inactive specific transcript (XIST) is a functional long non-coding RNA, which has been reported to inhibit the proliferation of cardiomyocytes and promote apoptosis via interacting with miR-130a-3p in myocardial infarction." (PMID 33889601, 2021).
prostate carcinoma (13 papers, 2017 to 2025). A carcinoma that arises from epithelial cells of the prostate gland. "Studies have shown that the lncRNA XIST regulates different cancers but in prostate cancer its underlying mechanism is still unclear." (PMID 34944867, 2021). "The expression of XIST is negatively correlated with metastasis and its low expression is associated with poor prognosis in prostate cancer patients." (PMID 34944867, 2021). "In gain and loss of function assays, we confirmed that XIST suppressed cellular proliferation and metastasis in prostate cancer both in vitro and in vivo." (PMID 29212233, 2017). "Our data suggested that miR-23a expression level was negatively associated with the expression of XIST in 62 prostate cancer patients." (PMID 29212233, 2017). "In our present study, we confirmed that miR-23a was highly expressed in prostate cancer samples and inversely associated with the expression of XIST." (PMID 29212233, 2017). "Lower levels of XIST are likely linked to more aggressive tumor behavior and reduced survival rates, suggesting a pivotal role in mediating racial differences in gene expression between AF and EU prostate cancer patients." (PMID 40004558, 2025). "Furthermore, in gain and loss of function assays, we verified that overexpressing XIST induced significant suppression in cell proliferation, cell migration and invasion ability of prostate cancer cells both in vitro and in vivo." (PMID 29212233, 2017). "High levels of XIST enhance the invasiveness and proliferation of prostate cancer cells by sequestering miRNA-96-5p, miRNA-153-3p, and miRNA-182-5p." (PMID 40308577, 2025). "In this study, we constructed an XIST ceRNA network to investigate the potential regulatory mechanism by which XIST influences prostate cancer growth." (PMID 36038831, 2022). "Our in vitro experiments showed that the expression level of XIST was positively correlated with the invasion and proliferation of prostate cancer cells, but negatively correlated with apoptosis." (PMID 36038831, 2022). "XIST also showed high expression levels in prostate cancer patients which was also consistent with of the results from the prostate cancer cell lines." (PMID 36038831, 2022). "The ceRNA network is the most important functional mode of lncRNAs in the pathogenesis of prostate cancer and other tumours, therefore the downstream targets of XIST were predicted and the ceRNA network was built." (PMID 36038831, 2022). "XIST has been known to be responsible for suppressing cellular proliferation and metastasis in prostate cancer cell lines and for negatively regulating miR-23a expression." (PMID 34944867, 2021). "A downregulation of XIST in prostate cancer specimens and cell lines that leads to a low expression of XIST has been correlated with advanced tumor stage in patients with prostate cancer and a poor prognosis in those patients." (PMID 34944867, 2021). "Based upon our proposed method, prostate cancer was predicted to be associated with H19, MALAT1, CDKN2B-AS1, HOTAIR, PCAT1, SRA1, XIST." (PMID 29671405, 2018). "To better understand the correlation between lncRNA XIST and clinical features of prostate cancer patients, we analyzed clinical data that we collected from 62 prostate cancer patients." (PMID 29212233, 2017). "In conclusion, our study revealed that lncRNA XIST was markedly decreased in prostate cancer specimens and functioned as a tumor suppressor, which played a key role in regulating malignancies in prostate cancer." (PMID 29212233, 2017). "In the current study, we found that XIST was down-regulated in prostate cancer specimens and cell lines." (PMID 29212233, 2017). "Taken together, these findings indicated that over-expression of XIST inhibited cell proliferation, migration and invasion in prostate cancer cells." (PMID 29212233, 2017). "We found that the expression of XIST was considerably reduced in the 3 prostate cancer cell lines compared to RWPE1." (PMID 29212233, 2017).